SULT1A1 (sulfotransferase family 1A member 1)
Diseases named in the same sentence as SULT1A1 in open-access papers (continued):
Sharing a sentence is not in itself a finding about the gene and the disease.
tumor (21 papers, 2005 to 2025). "The SULT1A1*1/*1 high-activity genotype was associated with age at diagnosis <60 years (OR = 7.14, CI = 1.23–50, P = 0.02) and tumor size ≤2 cm (OR = 14.28, CI = 2.17–100, P = 0.02)." (PMID 16280036, 2005). "We observed that the high-activity SULT1A1 genotype (SULT1A1*1/*1) was associated with a greater frequency of small tumor size (≤2 cm) when compared with the group of individuals with other genotypes." (PMID 16280036, 2005). "We determined that the SULT1A1*1/*1 high-activity genotype was associated with tumor size ≤2 cm (odds ratio = 2.63, 95% confidence interval = 1.25–5.56, P = 0.02)." (PMID 16280036, 2005). "Quercetin conferred resistance of SULT1A1-proficient HCT116 cells to all three compounds, strengthening the notion of a causal relationship between SULT1A1 activity and tumor suppression by RITA, AF, and ONC-1." (PMID 32727562, 2020). "Other laboratories have reported that expression of SULT1A1 is very low in normal breast tissue as compared to tumor tissue." (PMID 24393253, 2014). "SULT1A1 CNVs were analysed by quantitative real-time PCR with TaqMan probes (Life Technologies, Carlsbad, CA, USA) comparing DNAs from tumour and blood from each MBCs included in the study." (PMID 23711090, 2013). "In particular, SULT1A1 gene deletion (RQ = 0.5) was observed indicating the presence of a single copy of SULT1A1 gene in the 10 tumour samples compared with two copies (RQ = 1) detected in the corresponding blood samples." (PMID 23711090, 2013). "SULT1A1 gene copy number differences were found to occur in tumour compared with matched blood samples in 10 of the 72 MBCs (13.9%)." (PMID 23711090, 2013). "We found that a quite relevant proportion of MBCs (about 14%) showed SULT1A1 gene deletion and, interestingly, that the deletion was significantly found in BRCA2-associated tumours." (PMID 23711090, 2013). "It was found that of 149 GM cases, 42.0%, 27.1% and 19.6% showed similar SULT1A1, 1C2 and 4A1 levels (>++) as that of tumor-surrounding tissues and the remaining parts showed reduction (+) and even absence (−) of SULT1A1, 1C2 and 4A1 expression." (PMID 22096581, 2011). "The group of SULT1A1*1/*1 and UGT1A1*1/*1, UGT1A1*1/*33 and UGT1A1*33/*33 high-activity genotypes was associated with tumor size ≤2 cm (OR = 9.02, CI = 1.59–51.31, P = 0.01) and low tumor grade (OR = 10, CI = 1.09–100, P = 0.04)." (PMID 16280036, 2005). "Among all cases we determined that individuals with the SULT1A1*1/*1 genotype (high activity) were most likely to present with a small tumor size (≤2 cm; OR = 2.63, CI = 1.25–5.56, P = 0.02) compared with individuals with other SULT1A1 genotypes." (PMID 16280036, 2005). "In summary, the present data reveal that YC-1 or similar compounds might be therapeutically helpful against SULT1A1-expressing neoplasms, especially primary liver tumors." (PMID 37311747, 2023). "In addition to YC-1, the study identified additional small molecules showing similar SULT1A1-dependent anti-tumor activities." (PMID 37311747, 2023). "Further studies are needed to determine why SULT1A1 had a low TON in tumor tissues." (PMID 28634336, 2017). "In tumor tissues, correlation coefficients greater than 0.593 were found between protein amounts and enzymatic activities in all the measured SULTs, particularly SULT1A1, which showed a high correlation coefficient of 0.950." (PMID 28634336, 2017). "In agreement with the in vitro findings, tissue microarray-based IHC for the three brain-associated SULTs revealed diverse SULT expression patterns in 149 GM cases of which 42.0%, 27.1% and 19.6% showed similar levels of SULT1A1, 1C2 and 4A1 as that of tumor surrounding tissues." (PMID 22096581, 2011). "We then asked whether a genetic variation in UGT1A1 or SULT1A1 influenced specific tumor phenotypes." (PMID 16280036, 2005).
tumor (continued). "From previous study we knew that SULT1A1 was an important enzyme in xenobiotic metabolism because it had broad substrate specificity with a high affinity for many compounds, furthermore SULT immunoreactivity was associated with tumor size (P = 0.0030) or lymph node status (P = 0.0027)." (PMID 20663177, 2010). "The activities of SULT1A1, SULT1B1, SULT1E1 and SULT2A1 in 9 of 10 samples showed a significant decrease in tumor tissues relative to matched pericarcinomatous tissues, whereas the activities of SULT1A3 in 7 of 10 samples increased." (PMID 28634336, 2017). "The mRNA expression levels of SULT1A1, SULT1A3, SULT1E1, and SULT2A1 decreased or drastically decreased in 90% of the tumor samples in comparison with the matched pericarcinomatous samples." (PMID 28634336, 2017). "This unique pattern of tumor sensitivity has been attributed to the need for intracellular bioactivation by cytochrome P450 1A1 (CYP1A1) and sulfotransferase 1A1 (SULT1A1) to convert AF to DNA-damaging species." (PMID 24058584, 2013). "Individuals who carried genotypes predicting both high-activity SULT1A1*1/*1 and high-activity UGT1A1*1/*1, UGT1A1*1/*33 and UGT1A1*33/*33 presented with low tumor grade (grade 1) (OR = 2.56, CI = 1.04–6.25, P = 0.05)." (PMID 16280036, 2005). "Individuals with both SULT1A1 and UGT1A1 high-activity genotypes had low tumor grade (odds ratio = 2.56, 95% confidence interval = 1.04–6.25, P = 0.05)." (PMID 16280036, 2005). "It has been widely described that Nrf2 overexpression in different tumor types contributes to pro-oncogenic processes and chemoresistance by promoting the transcription of antioxidant (NQO1), detoxifying (SULT1A1), and anti-apoptotic (BCL-2) enzymes with ARE element." (PMID 39034849, 2024). "Thus, using probe substrates, we systematically measured the metabolic functions of SULT1A1, SULT1A3, SULT1B1, SULT1E1, and SULT2A1 in tumor S9 (tHLS9-pooled), pericarcinomatous S9 (nHLS9-pooled), and reference pooled normal human S9 (rHLS9-pooled)." (PMID 28634336, 2017). "Furthermore, we observed that individuals with both high-activity SULT1A1 and high-activity UGT1A1 genotypes were more likely to have a lower tumor grade than those with other genotypes." (PMID 16280036, 2005). "The statistical significance of the association between the interaction of high-activity SULT1A1 and UGT1A1 genotypes with low tumor grade, however, was no longer significant within the group of only Caucasian women (OR = 1.96, CI = 0.75–5.00, P = 0.19)." (PMID 16280036, 2005). "The differential expression of SULT1A1 in tumor tissues versus neighboring normal tissues suggests that expression of SULT1A1 in tumors, but not the germ line SULT1A1 haplotypes, is a more appropriate biomarker to identify responders for therapeutics activated by SULT1A1." (PMID 25514600, 2015). "The TONs of SULTs other than SULT1A1 in the tumor tissues were nearly identical to the values observed in the pericarcinomatous tissues and healthy samples (P > 0.05), thereby suggesting that the catalytic efficiency of SULTs was not seriously impaired in tumor S9." (PMID 28634336, 2017). "Hence, the data showed that the tumor cells usually expressed lower amounts of SULT proteins in comparison with pericarcinomatous tissues, but those SULT proteins appeared to be just as active, with the exception of SULT1A1, which appeared to be moderately less active." (PMID 28634336, 2017). "Using TONs of SULTs as a measurement of catalytic efficiency, we found that with the exception of that for SULT1A1, TON did not change in the tumor vs. pericarcinomatous tissues, even with a large decrease in activities or expressions in 90% of the subjects." (PMID 28634336, 2017).
infection (2 papers, 2016 to 2025). The state of being infected such as from the introduction of a foreign agent such as serum, vaccine, antigenic substance or organism. "By contrast, there was a marked reduction of DNA products longer than 2 kb in length at 8 h post-infection in cells deficient in SULT1A1." (PMID 26906565, 2016). "To determine the step in HIV-1 replication that is influenced by SULT1A1, we monitored the effect of SULT1A1 siRNA #2 on early steps of virus replication at 24 h post-infection." (PMID 26906565, 2016). "RNAi-knockdown of SULT1A1 in MDMs leads to a substantial decrease in infection by both pseudotyped and replication-competent HIV-1 vectors, as well as by a SIVagm vector." (PMID 26906565, 2016). "Each of the 3 SULT1A1 siRNAs also reduced the levels of infection seen with a VSV-G-pseudotyped HIV-1 NL43 virus vector as judged by monitoring expression of the firefly luciferase reporter enzyme from the viral genome." (PMID 26906565, 2016). "The fact that all three SULT1A1-directed siRNAs reduced viral gene expression following infection strongly argues against an indirect off-target effect being responsible for this effect." (PMID 26906565, 2016). "Taken together, these results demonstrate that SULT1A1 is important for efficient virus gene expression following infection of MDMs with single cycle HIV-1 and SIV vectors and with replication-competent HIV-1." (PMID 26906565, 2016). "MDMs that were transfected with control siRNA or with SULT1A1-siRNA#2 were challenged with the replication-competent CCR5-tropic HIV-1 Env + JM1186 virus encoding Renilla luciferase and luciferase expression was assayed three days post infection." (PMID 26906565, 2016).
adenocarcinoma (1 paper, 2015). A common cancer characterized by the presence of malignant glandular cells. "According to GSE29060 data, in HT-29 adenocarcinoma cells after a demethylation treatment 4 transcripts showed a minimally decreased expression (TIMP1, FADS1, CYP27B and SULT1A1), while PTGS2 was found to be upregulated." (PMID 26482433, 2015).
neurodegenerative disease (1 paper, 2024). A disorder of the central nervous system characterized by gradual and progressive loss of neural tissue and neurologic function. "Furthermore, Sult1a1 was observed among the top10, which was reported in several studies on neurodegenerative diseases and it was found among the top10 in one of the brain studies (GSE102204) as well." (PMID 39529156, 2024).
neurodevelopmental disorder (1 paper, 2021). A behavioral and cognitive disorder with onset during the developmental period that involves impaired or aberrant development of intellectual, motor, or social functions. "Accordingly, we speculate that excess FA-induced overexpression of Sult1a1 and/or Tph2 might disturb neurotransmitter metabolism, and therefore contribute to neurodevelopmental disorders." (PMID 35010941, 2021).
SULT1A1 also shares sentences with these, for which no sentence is quoted: prostate carcinoma (4 papers); Alzheimer disease (2); autoimmune encephalitis (2); depression (2); heart disease (2); acute lymphoblastic leukemia (1); acute myocardial infarction (1); Anxiety (1); autoimmune thyroid disease (1); Autoimmunity (1); brain tumors (1); cardiovascular disease (1); Cirrhosis (1); colorectal adenoma (1); COVID-19 (1); Crohn disease (1); cutaneous leishmaniasis (1); diabetes (1); dilated cardiomyopathy (1); gynecological tumors (1); heart failure (1); hypogonadism (1); immune system diseases (1); Insulin resistance (1); invasive breast carcinoma (1); juvenile idiopathic arthritis (1); kidney injury (1); Lipedema (1); liver cirrhosis (1); liver diseases (1).
A further 22 diseases each share a sentence with SULT1A1 in 1 paper.